MIR802 (microRNA 802)
Synonyms: hsa-mir-802; MIRN802
Gene: MicroRNA gene on chromosome 21 (35,720,715 to 35,720,808, forward strand). Ensembl gene ENSG00000211590.
Gene Ontology:
Biological process: miRNA-mediated post-transcriptional gene silencing
Homologues: Orthologues: chimpanzee ptr-mir-802 (99% identical), macaque mml-mir-802 (98% identical), dog MIR802 (90% identical), guinea pig MIR802 (86% identical), rat Mir802 (86% identical), rabbit MIR802 (60% identical), pig ssc-mir-802 (56% identical).
Diseases named in the same sentence as MIR802 in open-access papers:
MIR802 is named in the same sentence as 8 diseases in open-access papers, as found by Europe PMC text mining. Sharing a sentence is not in itself a finding about the gene and the disease. The quoted sentences say what the papers report.
Glucose intolerance (1 paper, 2024). Glucose intolerance (GI) can be defined as dysglycemia that comprises both prediabetes and diabetes. "As expected, Mir802 KI mice on a HFD exhibited progressive development of glucose intolerance and insulin resistance at 8 weeks, as compared to their WT littermates." (PMID 39589393, 2024). "Mir802 inhibitor treatment also ameliorated insulin resistance and glucose intolerance in DIO mice." (PMID 39589393, 2024). "In addition, the insulin resistance and glucose intolerance induced by an HFD were ameliorated by Mir802 depletion." (PMID 39589393, 2024). "Similarly, Macrophage depletion with CLOD-liposomes obviously alleviated the HFD-induced glucose intolerance in Mir802 KI mice, and abrogated the differences of these metabolic indicators between Mir802 KI mice and WT mice." (PMID 39589393, 2024).
Hyperglycemia (1 paper, 2024). An increased concentration of glucose in the blood. "We found that in Mir802 KI mice, HFD induced weight gain and hyperglycemia both in male and female." (PMID 39589393, 2024). "The knockout of Mir802 in adipose tissue did not alter food intake, body weight, glucose levels, and adiposity compared with their WT littermates in both males and females when they were fed with NCD; however, this approach could prevent HFD-induced weight gain and hyperglycemia." (PMID 39589393, 2024).
Hyperinsulinemia (1 paper, 2024). An increased concentration of insulin in the blood. "Furthermore, macrophage depletion also led to recover hyperinsulinemia and HOMA-IR in Mir802 KI mice after the treatment." (PMID 39589393, 2024).
Impaired glucose tolerance (1 paper, 2024). An abnormal resistance to glucose, i.e., a reduction in the ability to maintain glucose levels in the blood stream within normal limits following oral or intravenous administration of glucose. "In the liver, Mir802 is induced by obesity and impaired glucose tolerance, and it attenuates insulin sensitivity by downregulation of Hnf1b." (PMID 39589393, 2024).
Insulin resistance (1 paper, 2024). Increased resistance towards insulin, that is, diminished effectiveness of insulin in reducing blood glucose levels. "The present observations indicate that Mir802 inhibitors might offer a novel approach to prevent diseases associated with insulin resistance." (PMID 39589393, 2024). "Mir802 expression in visceral fat was progressively increased with the development of dietary obesity, whereas adipose-selective ablation of Mir802 protected mice from exacerbation of meta-inflammation and insulin resistance caused by dietary stress." (PMID 39589393, 2024). "We hypothesized that the elevation of Mir802 in adipocytes is associated with adipose inflammation and insulin resistance." (PMID 39589393, 2024). "Through in vitro experiments, we found that Mir802 was dramatically increased in the insulin resistance cell models." (PMID 39589393, 2024). "Taken together, these findings support the notion that elevated Mir802 induces macrophage recruitment and polarization at least partly via downregulation of Traf3, thereby leading to adipose tissue inflammation and insulin resistance." (PMID 39589393, 2024). "Our findings indicate that Mir802 has essential roles in the initiation and maintenance of adipose tissue inflammation and systemic insulin resistance." (PMID 39589393, 2024). "Adipose tissue-specific knockout of Mir802 lowered macrophage infiltration and ameliorated systemic insulin resistance." (PMID 39589393, 2024). "The findings that systemic insulin resistance is ameliorated by Mir802 depletion and is aggravated by adoptive transfer of Mir802 mimics strongly suggest that Mir802-dependent adipose inflammation has an impact on systemic metabolism." (PMID 39589393, 2024). "To better understand the role of Mir802 in regulating macrophage-mediated adipose tissue inflammation and insulin resistance, we next set out to identify the target genes of Mir802 in adipocytes." (PMID 39589393, 2024). "Genes that are crucial for meta-inflammation and insulin resistance were directly affected by the enhancement of Mir802 in adipose tissue." (PMID 39589393, 2024). "In this study, we found that Mir802 promotes adipose tissue inflammation and insulin resistance by targeting TRAF3 in adipocytes." (PMID 39589393, 2024). "Thus, increased adipose tissue inflammation resulting from Mir802 overexpression contributed, in large part, to systemic insulin resistance in Mir802 KI mice." (PMID 39589393, 2024). "The high level of Mir802 expression in visceral fat may partly explain why this adipose depot is more prone to inflammation and is closely related to insulin resistance." (PMID 39589393, 2024). "Adipose tissue-specific overexpression of Mir802 in mice fed an HFD exhibited increased severity of systemic insulin resistance compared with wild-type (WT) mice, which was accompanied by macrophage infiltration and a marked increase in adipose tissue inflammation." (PMID 39589393, 2024).
Obesity (1 paper, 2024). Accumulation of substantial excess body fat. "Adipocyte Mir802 levels are positively associated with obesity in mice and humans." (PMID 39589393, 2024). "Here, we showed that the increasing trend of Mir802 in adipocytes is an early event during the development of adipose tissue obesity induced by an HFD." (PMID 39589393, 2024). "The same phenomenon was also observed in RNA-FISH analysis, indicating that upregulation of Mir802 in the adipose tissue during obesity is conserved in humans." (PMID 39589393, 2024). "We observed that Mir802 progressively increased in adipose tissue from week 4 with the development of obesity in mouse models of genetic and dietary obesity." (PMID 39589393, 2024). "Although previous studies have found that Mir802 was up-regulated in the adipose tissue during obesity, the function of Mir802 was focused on cancers, liver, small intestine, and pancreas." (PMID 39589393, 2024). "Adipose tissue–specific ablation of Mir802 protects mice from obesity-induced metabolic dysfunction." (PMID 39589393, 2024). "Obesity induced Mir802 elevation precedes macrophage accumulation." (PMID 39589393, 2024). "Given the striking effects of adipose-selective overexpression of Mir802 on metabolism, we next investigated whether selectively ablated Mir802 in adipose tissue could mitigate metabolic disturbance and inflammation induced by obesity." (PMID 39589393, 2024).
MIR802 also shares sentences with these, for which no sentence is quoted: cancer (1 paper); inflammatory bowel disease (1).